AHR (aryl hydrocarbon receptor)
Diseases named in the same sentence as AHR in open-access papers (continued):
Sharing a sentence is not in itself a finding about the gene and the disease.
colorectal cancer (continued). "Similar to the results obtained for the other cancer types, the nuclear and cytosolic AhR expression were significantly positively correlated in colorectal cancer." (PMID 38680496, 2024). "Formate derived from the microbiome promotes colorectal cancer tumor invasion by activating AHR signaling." (PMID 37179416, 2023). "Compared with A. muciniphila higher tissues, tumor areas had more AhR + cells in A. muciniphila lower tissues, which positively correlated with the clinical stage of colorectal cancer." (PMID 37781044, 2023). "Quercetin and kaempferol have many of the same targets, such as AKT1, AHR, BCL2, NR4A1, etc., and AHR can inhibit the development of colorectal cancer 119-121." (PMID 37497415, 2023). "What is more, Activation of the Wnt/β-catenin pathway induced by AhR is the initiating event in the majority of human colorectal cancers and one of the key regulators of CRC pathogenesis." (PMID 37781044, 2023). "In colorectal cancer cells Memo1 promoter activity is increased in response to the transcription factors Aryl hydrocarbon receptor/ Aryl hydrocarbon receptor nuclear‐translocator complex, indicating some intestinal disease relevance." (PMID 32291966, 2020). "The phenomenon that AhR degrades β-catenin was clearly demonstrated in several colorectal cancer cell lines, DLD-1, HCT116, and SW480." (PMID 31675361, 2019). "AhR is overexpressed in blood tumors, such as T-cell leukemia and lymphoma, and solid tumors, such as glioblastoma, ovarian cancer, lung cancer, liver cancer, and colorectal cancer." (PMID 41155994, 2025). "Its dual mechanism of inhibiting AhR and PD-1/PD-L1 pathways, combined with favorable pharmacokinetics and strong in vivo efficacy, highlights its promise as a therapeutic candidate for colorectal cancer, particularly in combination with existing immunotherapies." (PMID 41155994, 2025). "Additionally, A. muciniphila inhibits tryptophan metabolism via the AhR/β-catenin signaling pathway, contributing to the suppression of colorectal cancer progression." (PMID 40658318, 2025). "Similarly, SR-1, a known AHR antagonist, reduced the viability of colorectal cancer cells but had little effect on normal colon CCD-18Co cells." (PMID 41155994, 2025). "In colorectal cancer cells, the nuclear AhR expression was higher than the cytosolic one." (PMID 38680496, 2024). "An increasing multitude of reports suggest a tumor regulatory role for AhR in colorectal cancer." (PMID 38807762, 2024). "Furthermore, the antitumor effectiveness of A. muciniphila was abolished either in a human colon cancer tumor model induced by subcutaneous transplantation of AhR-silenced CRC cells, or AhR-deficienty spontaneous colorectal cancer model." (PMID 37781044, 2023). "This suggests that in colorectal cancer, the combination of the two may promote the expression of AHR, inhibit the expression of NR4A1, and achieve the synergistic effect of inhibiting CRC." (PMID 37497415, 2023). "Downregulation of AhR also resulted in a marked reduction in Wnt/β-catenin signaling, which suggest that Trp/AhR-mediated Wnt/β-catenin pathway is intricately involved in the growth and maintenance of colorectal carcinoma." (PMID 37781044, 2023). "The growing link between environmental factors such as dietary intake, pollutants and microbial dysbiosis in colorectal cancer etiology, places AHR at a pivotal position in influencing the delicate balance between controlled regeneration and malignant transformation." (PMID 35383166, 2022). "Subsequently, TDO2 activates the Kyn-AhR pathway, enhances glycolysis, promotes tumor cell proliferation, and secretes CXCL5 to attract immunogenic tumor-associated macrophages into the tumor microenvironment, thereby suppressing tumor immunity and influencing the progression of colorectal cancer." (PMID 40136551, 2025). "In colorectal cancer, Lactobacillus gallinarum‐derived ICA enhances anti‐PD‐1 therapy by regulating the IDO1/Kyn/AhR axis." (PMID 40103267, 2025).
colorectal cancer (continued). "The study further explains that activation of AhR by Kyn, which is generated through the catalysis of TDO2, directly contributes to the promotion of liver metastasis in colorectal cancer." (PMID 40136551, 2025). "Deletion of AHR in the APCS580/+; KRASG12D/+ mouse model of colorectal cancer promotes proliferation and tumor growth and decreases mouse survival rate." (PMID 38807762, 2024). "Mechanistically, our study showed that the AhR controls BOLD-100 induced CYP1A1 levels, ROS production, and ATR activation in BRAFMT colorectal cancer cells." (PMID 39083088, 2024). "Here, we evaluated the AhR expression and distribution in five solid cancer types: HNSCC, bladder cancer, colorectal cancer, esophageal cancer, and non-small cell lung cancer (NSCLC)." (PMID 38680496, 2024). "Involvement of the AhR-regulated MMP-1/EGFR signaling in colorectal cancer pathogenesis was indicated as the suppression of MMP-1, a gene induced by AhR, led to the improvement of colorectal cancer by inhibiting EGFR-downstream PI3K/AKT signaling." (PMID 39211042, 2024). "According to colorectal cancer research, tryptophan metabolites derived from anaerobic bacteria, such as trans-3-indoleacrylic (IDA), act as endogenous ligands for the aryl hydrocarbon receptor (AHR), leading to the transcriptional upregulation of ALDH1A3 expression." (PMID 40708788, 2025). "In addition, indoxyl sulfate can activate the aryl hydrocarbon receptor and Akt signaling pathways, inducing epidermal growth factor receptor (EGFR) expression and promoting colorectal cancer progression." (PMID 41257289, 2025). "However, further translational studies are required to elucidate the role of AhR in various stages of colorectal cancer (CRC) progression and to guide AhR as a potential therapeutic target for CRC." (PMID 39767818, 2024). "C. albicans mediates the up-regulation of macrophage glycolytic pathway, and up-regulates the expression and secretion of IL-7, and then induces type 3 intrinsic lymphocytes (ILC3) to express high levels of IL-22 through AhR and STAT3 pathways, which aggravates the progression of colorectal cancer." (PMID 37333850, 2023).
Insulin resistance (57 papers, 2011 to 2025). Increased resistance towards insulin, that is, diminished effectiveness of insulin in reducing blood glucose levels. "Specifically, compared with WT rats subjected to HFHFrHCD, AHR deficiency aggravated HFHFrHCD-induced liver injury, insulin resistance, and hepatic lipid accumulation (particularly triglycerides and cholesterol)." (PMID 41516226, 2025). "In summary, AhR signaling pathway is linked to insulin resistance through several mechanisms, including its influence on PPAR-α, circadian rhythms and inflammation." (PMID 41440753, 2025). "Activation of AhR by environmental toxins like dioxins promotes insulin resistance, while deficiency of AhR can protect against it." (PMID 41440753, 2025). "Achieving this goal requires a deeper understanding of the mechanisms underlying the development of insulin resistance, with particular attention to the aryl hydrocarbon receptor (AhR)." (PMID 41440753, 2025). "We discovered that AHR deficiency can elevate plasma transaminase levels, increase hepatic triglyceride (TG) and total cholesterol (TC), and exacerbate insulin resistance (IR) under an overnutrition environment." (PMID 41516226, 2025). "Overall, the precise effect of AhR on insulin resistance appears to depend on factors such as tissue type and the specific ligands activating AhR, with AhR deficiency generally exerting a protective effect against insulin resistance." (PMID 41440753, 2025). "Our results revealed that BPA suppressed GLUT4 expression and induced abnormal glucose metabolism by activating AhR, causing insulin resistance, and is thus a potential contributor to the development of PCOS." (PMID 38200540, 2024). "All TCDD-mediated effects related to insulin resistance were still observed in aryl hydrocarbon receptor (AhR)-deficient myocytes and prevented by MitoTEMPO, a mitochondria-targeting ROS scavenger." (PMID 36358481, 2022). "Using AhR-deficient (AhR−/−) mice, we next examined the role of AhR in H-Exo-mediated insulin resistance." (PMID 33431899, 2021). "Here, the authors report a mechanism that underlies the development of diet induced insulin resistance through the activation of an aryl hydrocarbon receptor mediated signalling pathway in the liver by faecal exosomes derived from intestinal cells." (PMID 33431899, 2021). "Thus, PPARα activation in the liver provides a mechanism underlying AhR-mediated insulin resistance, while AhR deficiency protects mice from insulin resistance, potentially via PPARα downregulation." (PMID 41440753, 2025). "Insulin resistance associated with periodontitis was reduced by supplementing with an AhR agonist—Ficz (6-formylindolo (3,2-b) carbazole), where the restoration of gut barrier function may have been a significant factor." (PMID 40862144, 2025). "Moreover, glucose levels, insulin resistance, and inflammatory cytokines were also lower in AhR-deficient mice than in wild-type mice after high-fat diet feeding." (PMID 37749614, 2023). "Furthermore, hepatic activation of the PPAR-α pathway provides a mechanism underlying AhR-mediated insulin resistance." (PMID 21849270, 2011). "Since exposure to environmental PAHs can cause insulin resistance, abdominal obesity and leukopenia, too, one might attribute the adverse effects of clozapine—probably in synergy with other AhR ligands—to AhR activation." (PMID 34979820, 2022). "The indirubin, an AhR agonist, induced the secretion of IL-10 and IL-22 by activating AhR to prevent high-fat diet-induced insulin resistance in mice model." (PMID 39944639, 2025). "Bacteroides ovatus was reported to produce indoleacetic acid to fortify intestinal barrier function via activation of intestinal aryl hydrocarbon receptor to relieve insulin resistance." (PMID 40631381, 2025).
Insulin resistance (continued). "Disruption of circadian rhythm, peroxisome proliferator-activated receptor α (PPARα) signaling (a contributor to insulin resistance and T2DM), and AhR activation are implicated in T2DM development in individuals exposed to environmental pollutants." (PMID 41440753, 2025). "The net effect of AhR on insulin resistance appears to depend on tissue context and the nature of activating ligands." (PMID 41440753, 2025). "The role of AhR in tamoxifen-induced insulin resistance remains unexplored; however, given its metabolic effects and the established role of AhR in insulin resistance, a potential mechanistic link has been suggested." (PMID 41440753, 2025). "The following keywords were used: glucose metabolism/tolerance, insulin resistance/sensitivity, drug effects on glucose metabolism disorders, drug induced endocrine disorders, AhR." (PMID 41440753, 2025). "The metabolic effects of tamoxifen and its known role in insulin resistance suggest a potential link between AhR activation and tamoxifen-induced insulin resistance, although this connection remains to be fully elucidated." (PMID 41440753, 2025). "AhR activation can exacerbate insulin resistance by promoting proinflammatory signaling or potentially improve it by activating metabolic regulators such as FGF21." (PMID 41440753, 2025). "Elevated AhR expression correlates with higher levels of inflammatory markers and increased insulin resistance." (PMID 41440753, 2025). "Adipose tissue-specific AhR activation exacerbated insulin resistance, whereas adipose tissue-specific AhR deletion improved insulin sensitivity." (PMID 39941095, 2025). "ovatus-derived indoleacetic acid (IAA) was established as a key bioactive metabolite that fortifies intestinal barrier function via activation of intestinal aryl hydrocarbon receptor (AhR), leading to an amelioration in insulin resistance." (PMID 38868507, 2024). "To further confirm insulin resistance in AhR-driven ovarian granular cells, we tested the endogenous AhR agonist kynurenine (Kyn)." (PMID 38200540, 2024). "Studies in mice have also demonstrated EVs can play a critical role in the pathogenesis of insulin resistance via alteration in AhR signaling." (PMID 37982029, 2023). "Although the molecular mechanisms and mediators governing HFD-mediated insulin resistance and inflammation are unclear, one protein of interest in regulating the insulin response is AhR." (PMID 36499198, 2022). "It appears that AhR-specific adipose deletion protects females from leptin resistance and males from insulin resistance." (PMID 35887027, 2022). "We have recently shown that HFD feeding increases the expression of AHR which contributes to promoting insulin resistance in mice." (PMID 35154484, 2022). "In agreement with PCBs’ ability to activate nuclear receptors, several effects of PCBs in adipose tissue, including insulin resistance, were shown to be largely attributed to the modulation of the aryl hydrocarbon receptor (AhR)." (PMID 35202251, 2022). "In human cohort studies, we reported that elevated serum concentrations of AhR agonist mixture were surrogate biomarkers for the future development of diabetes, insulin resistance, and renal failure." (PMID 36499198, 2022). "Epidemiological studies link AhR activation by persistent organic pollutants (POPs) to insulin resistance." (PMID 35887027, 2022). "Overexpression of AhR leads to insulin resistance, while AhR-null mice have enhanced insulin sensitivity and improved glucose tolerance." (PMID 36499198, 2022). "On the other hand, the reduction in tryptophan in serum induces the insufficient production of AhR derived from gut microbiota decomposing the tryptophan, which brings about a series of metabolic disorders such as insulin resistance and inflammation." (PMID 34684645, 2021). "Here, we demonstrated that ginger-derived nanoparticles (GDNP) can prevent insulin resistance by restoring homeostasis in gut epithelial AhR signaling in mice fed a HFD." (PMID 33754048, 2021).
Insulin resistance (continued). "Altogether, GDNP prevents high-fat diet-induced insulin resistance by miR-375 mediated inhibition of the aryl hydrocarbon receptor mediated pathways over activated by HFD feeding." (PMID 33754048, 2021). "Sorting of miR-375 into exosomes via VAMP7 leads to prevention of insulin resistance mediated by bacterial indole and hepatic AhR." (PMID 33754048, 2021). "We further studied the possible role of elevated AHR transcripts in the pathogenesis of insulin resistance." (PMID 32849564, 2020). "We further studied the potential role of elevated AHR mRNA expression in the development of insulin resistance." (PMID 32849564, 2020). "Insulin resistance and depletion of glucose reserves may occur as a result of the activated AhR blocking the AKT kinase-glucose pathway." (PMID 41440753, 2025). "Leflunomide acts on molecular pathways implicated in insulin resistance, a central factor in T2DM, pathways in which AhR signaling may also be involved." (PMID 41440753, 2025). "The lack of AHR aggravated HFHFrHCD-induced elevation of plasma transaminase levels and degree of insulin resistance suggest that AHR deficiency promotes HFHFrHCD-induced liver injury." (PMID 41516226, 2025). "AhR activation may either exacerbate insulin resistance through the induction of proinflammatory signaling or potentially ameliorate it via activation of metabolic regulators such as FGF21." (PMID 41440753, 2025). "In high sugar-induced insulin resistance and diabetes complications, AhR is crucial for maintaining ILC3, promoting the development and maturation of ILC3, and stimulating the secretion of IL-22 by ILC3 to inhibit inflammation levels, thereby preserving intestinal homeostasis." (PMID 39944639, 2025). "Next, we assessed the role of AhR in BPA-mediated insulin resistance." (PMID 38200540, 2024). "Recent studies have revealed that indoles-induced aryl hydrocarbon receptor (AhR) activation may be an important way for bacteria to improve inflammatory status and insulin resistance." (PMID 36777348, 2023). "HIFs and AHR contribute to the regulation of metabolism, lipolysis, inflammation, endothelial dysfunction, thrombosis, and tissue injury that variously manifest in complications of tissue ischemia, insulin resistance, thrombosis, and fibrosis in CKD." (PMID 37814337, 2023). "Moreover, AhR−/− mice fed with HFD were partially protected against diet-induced glucose intolerance, suggesting a potential role of AhR in insulin resistance." (PMID 38136564, 2023). "In addition, PCB-induced AhR signaling was shown to be responsible for the development of adipose tissue inflammation, insulin resistance, and the inhibition of adipocyte energy expenditure and beiging." (PMID 35202251, 2022). "Intracellular miR-375 inhibits high-fat diet induced AhR which contributes to insulin resistance." (PMID 33754048, 2021). "Our data preliminarily suggest that AHR signaling might have a dual role in both development of insulin resistance and compensated β-cells function." (PMID 32849564, 2020). "The present data showed a remarkable linear correlation of AHR transcripts with Ln (HOMA-IR), indicating that AHR signaling may contribute greatly to insulin resistance." (PMID 32849564, 2020). "In this study, we hypothesized that coplanar PCBs promote insulin resistance and impair glucose homeostasis through adipocyte-specific AhR activation." (PMID 25734695, 2015). "The role of AhR in insulin resistance is complex, as it participates in the regulation of both metabolic and immune processes, disturbances of which may promote the development of insulin resistance." (PMID 41440753, 2025). "The beneficial mechanism of CTE on the prevention of insulin resistance could be mediated, at least in part, by increasing the transcription of antioxidant genes and reducing inflammatory genes 1 through the activation of the AhR pathway." (PMID 37239868, 2023). "Similarly, overexpression of AhR in the liver leads to insulin resistance." (PMID 34966278, 2021).